GFY (golgi associated olfactory signaling regulator)
Description:
Required for proper function of the olfactory system. May be involved in establishing the acuity of olfactory sensory signaling (By similarity).
Synonyms: Goofy
Tractability: Antibody: UniProt predicts a signal peptide or a membrane-spanning region.
Gene: Protein-coding gene on chromosome 19 (49,423,749 to 49,428,987, forward strand). Ensembl gene ENSG00000261949.
Subcellular location: Golgi apparatus membrane
Gene Ontology:
Biological process: sensory perception of smell
Cellular component: Golgi membrane; Golgi apparatus
Genetic constraint (gnomAD): Loss-of-function variants: 28 observed, 29.91 expected, observed/expected ratio (o/e) 0.94, 90% interval 0.69 to 1.28. The upper end of that interval is the gene's LOEUF score, 1.28, which puts it in group 5 of 6, group 1 being the genes least tolerant of losing a copy. Missense variants: 656 observed, 663.36 expected, observed/expected ratio (o/e) 0.99, 90% interval 0.93 to 1.05. Synonymous variants: 277 observed, 275.47 expected, observed/expected ratio (o/e) 1.01, 90% interval 0.91 to 1.11.
Homologues: Orthologues: chimpanzee GFY (99% identical), macaque GFY (90% identical), pig GFY (70% identical), dog GFY (68% identical), rabbit GFY (60% identical), mouse Gfy (53% identical), rat Gfy (53% identical).
Diseases named in the same sentence as GFY in open-access papers:
GFY is named in the same sentence as 2 diseases in open-access papers, as found by Europe PMC text mining. Sharing a sentence is not in itself a finding about the gene and the disease. The quoted sentences say what the papers report.
atherosclerosis (1 paper, 2023). A disease characterized by the build-up of fatty material and calcium deposition in the arterial wall resulting in partial or complete occlusion of the arterial lumen. "The GFY gene is mainly expressed in brain tissue, and has been associated to atherosclerosis through narrowing of the peripheral arterial vasculature." (PMID 37033211, 2023).
breast carcinoma (1 paper, 2024). "As a new discovery in this work, the olfactory signaling factor (GFY regulator) has not been evaluated for its role in breast cancer and may therefore be used as a prediction target for the diagnosis, treatment, or prognosis of breast cancer in the future." (PMID 39376611, 2024).